YTHDF3 (YTH N6-methyladenosine RNA binding protein F3)
Diseases named in the same sentence as YTHDF3 in open-access papers (continued):
Sharing a sentence is not in itself a finding about the gene and the disease.
cancer (continued). "Specifically, YTHDF3 was found to primarily target STAT3, a transcription factor that is frequently activated in human cancers and is involved in viral processes." (PMID 41453852, 2025). "GAS5 is negatively regulated by the m6A reader YTHDF3: m6A modification sites on lincRNA-GAS5 are recognized by YTHDF3, leading to GAS5 degradation and promoting cancer progression." (PMID 39280246, 2024). "YTHDF3 regulates YAP signaling by facilitating m6A-modified lncRNA GAS5 degradation and mediates cancer progression." (PMID 37537521, 2023). "The correlation between YTHDF3, MSI, and the TMB also suggested that YTHDF3 is closely related to the TME across cancers." (PMID 36606187, 2022). "Using the four-gene signature (YTHDF3, RBM15B, IGF2BP2, and TRMT61A), we constructed a nomogram to estimate 1-year and 3-year overall survival probabilities in patients from the eight selected TCGA cancer types." (PMID 40565233, 2025). "In numerous cancers, there is a consistent observation of dysregulated expression of key enzymes involved in m6A modification, including "writers" (such as METTL3, METTL14, WTAP), "erasers" (like FTO, ALKBH5), and "readers" (including YTHDF1, YTHDF2, YTHDF3)." (PMID 38270643, 2024). "ZDHHC20 inhibits the chaperone-mediated autophagic degradation of YTHDF3 through S-palmitoylation of Cys474, which can result in abnormal accumulation of the oncogenic product MYC and thereby promote the malignant phenotypes of cancer cells." (PMID 38821916, 2024). "ZDHHC20 inhibits chaperone-mediated autophagy of YTHDF3 through S-palmitoylation of Cys474, which can result in abnormal accumulation of the oncogenic product MYC and thereby support the malignant phenotypes of cancer cells." (PMID 38821916, 2024). "In addition, m6A‐recruited the binding proteins, YTHDC1, YTHDC2, YTHDF3, and FMR1 were inversely correlated, while HNRNPC, HNRNPA2B1, YTHDF1, and RBMX positively correlated TSs in most cancer types." (PMID 36239411, 2023). "Although the current study provides an overall picture of YTHDF3 in some cancers, one limitation of this work is that a detailed analysis of YTHDF3 in pan-cancer is lacking." (PMID 36606187, 2022). "In order to investigate the role of YTHDF3 in HCC, we performed immunohistochemistry (IHC) of paraffin sections from carcinoma and surrounding tissues of 466 patients diagnosed with HCC from July 2015 to December 2017 to study protein expression of YTHDF3 in HCC." (PMID 36471428, 2022). "Our results indicate that the YT521-B homology (YTH) domain family (“readers”), especially YTHDF1, YTHDF3, and YTHDC2, might play a significant role in the detection, progression, and prognosis of COAD, indicating that they are promising cancer biomarkers." (PMID 32596399, 2020). "Interestingly, we observed a statistically significant negative correlation between YTHDF3 expression levels and the degree of T-cell immune infiltration in many types of cancer." (PMID 36606187, 2022). "Our results revealed that in GBM cancer cells, expression of CD274 (PD-L1), PDCD1LG2 (PD-L2), LGALS9 (Galectin-9), and PVR (CD155) were positively correlated with the expression of multiple m6A regulators, especially YTHDF2, YTHDF3, LRPPRC, METTL3, RBM15B, FTO, and ALKBH5." (PMID 35558067, 2022). "YTHDF3 was enriched in mTOR signaling pathway (NES = 1.98, p = 0.021), neurotrophin signaling pathway (NES = 1.98, p = 0.023), Notch signaling pathway (NES = 2.10, p = 0.012), pathways in cancer (NES = 1.84, p = 0.047) and Wnt signaling pathway (NES = 1.86, p = 0.042)." (PMID 33362863, 2020). "The expression of YTHDF2 in cancer tissues was also up-regulated (p < 0.05), while those of RRP8, YTHDC1, and YTHDF3 were not significantly different." (PMID 34195072, 2021). "Although YTHDF2, YTHDF3, and YTHDC1 showed essential roles in multiple cancer types, to date, no research on these regulators in COAD has been conducted." (PMID 32596399, 2020).
infection (15 papers, 2018 to 2025). The state of being infected such as from the introduction of a foreign agent such as serum, vaccine, antigenic substance or organism. "Denise and colleagues found that knocking out YTHDF3 in human CD4+ T cells increases the risk of infection, and YTHDF3 acts as a limiting factor for human immunodeficiency virus (HIV)." (PMID 34630412, 2021). "The mRNA abundance of methyltransferase METTL3, and m6A-specific binding protein YTHDF2 and YTHDF3 significantly increased from 18 h to 24 h after infection." (PMID 40663568, 2025). "Previous study showed that knockout of YTHDF3 in human CD4+ T-cells increases infection supporting the role of YTHDF3 as a restriction factor." (PMID 37726690, 2023). "The expression of YTHDF3 mediated by siRNA can inhibit the infection efficiency of B. mori nuclear polyhedrosis virus (BmNPV)." (PMID 36009021, 2022). "Our data suggest that YTHDF3 depletion affects the host cell response to PVSRIPO infection at a step between type I/III IFN release and p-STAT1(Y701) induction, which points to a defect in IFN-dependent JAK/STAT1 pathway activation." (PMID 33849973, 2021). "YTHDF3 depletion enhanced viral translation and replication exclusively in cell lines that mount robust, protective innate antiviral responses to infection." (PMID 33849973, 2021). "Once incorporated, YTHDF3 proteins limit infection in the new target cell, specifically, at the reverse transcription step." (PMID 34205979, 2021). "To further test the role of the JAK/STAT pathway in mediating the stimulatory effect of YTHDF3 knockdown on PVSRIPO, we pretreated HeLa cells with IFN-α prior to infection and assessed the levels of viral translation upon YTHDF3 depletion." (PMID 33849973, 2021). "The principal effect of YTHDF3 depletion on the innate host response to PVSRIPO infection was dampened induction of ISGs (STAT1, MDA5, IFIT1, ISG15, OAS1)." (PMID 33849973, 2021). "In A375 cells, YTHDF3 depletion inhibited ISG induction that was triggered by PVSRIPO infection or poly(I:C) transfection." (PMID 33849973, 2021). "YTHDF3 proteins are incorporated into HIV particles in a nucleocapsid-dependent manner permitting the m6A reader protein to limit infection in the new target cell at the step of reverse transcription." (PMID 32053707, 2020). "Taken together, these results indicate that virion incorporated YTHDF3 alone is sufficient to negatively regulate viral infectivity in the next round of infection by limiting production of late RT products." (PMID 32053707, 2020). "We found that knockout of YTHDF3 in human CD4+ T-cells increases infection supporting the role of YTHDF3 as a restriction factor." (PMID 32053707, 2020). "We found that the YTHDF3 protein is incorporated into egressing virions in a nucleocapsid dependent manner, limiting the efficiency of the next round of infection." (PMID 32053707, 2020). "Depending on the donor, CD4+ T cells with reduced YTHDF3 expression were between 2.5 and 7-fold more susceptible to infection compared to CD4+ T cells electroporated with the non-targeting control." (PMID 32053707, 2020). "By producing single cycle viruses in YTHDF3 deficient cells with and without YTHDF3 complementation, we show that virion-incorporated YTHDF3 is sufficient to limit infection of CD4+ T cells by acting at the step of reverse transcription." (PMID 32053707, 2020). "Importantly, YTHDF3-/- mice were protected against infection with VSV." (PMID 34205979, 2021). "Dual depletion of YTHDF3 and DDX5 significantly lowered infection efficiency beyond single YTHDF3 depletion." (PMID 38649412, 2024). "In T3M4 cells, with active baseline STAT1 signaling, YTHDF3 depletion diminished innate activation at 0 to 8 hpi, during the critical early phase of PVSRIPO infection." (PMID 33849973, 2021).
infection (continued). "Deciphering the effects of YTHDF3 depletion on the innate host response to PVSRIPO infection indicated that the YTHDF proteins act at a step after IFN-β/IFN-λ1 release, implicating YTHDF3 as a mediator of JAK/STAT1 signaling." (PMID 33849973, 2021). "Here we report that the m6A reader protein YTHDF3 is incorporated into HIV particles in a nucleocapsid-dependent manner and reduces viral infectivity in the next cycle of infection." (PMID 32053707, 2020). "Here we investigated how the m6A reader protein YTHDF3 impacts the early steps of the HIV life cycle in the next round of infection." (PMID 32053707, 2020). "To determine if YTHDF3 is a factor involved in the innate antiviral response, we depleted YTHDF3 in A375 and T3M4 cells prior to infection with PVSRIPO (MOI 10) or transfection with high molecular weight (HMW) poly(I:C) and examined activation of antiviral signaling." (PMID 33849973, 2021). "We compared four different YTHDF3 antibodies and two different lots of the same antibody using cell lysates obtained from the A3R5-Rev-GFP-NTCg1 or YTHDF3g1 T cell lines used for the spreading infection experiments." (PMID 32053707, 2020). "Upon infection with CVB3, the results revealed that the knockdown of YTHDF1 and YTHDF2 resulted in significant reductions in CVB3 RNA copies, VP1 proteins, viral titres and GFP expression, whereas the knockdown of YTHDF3 led to a decrease in only CVB3 RNA copies and GFP expression." (PMID 39339923, 2024). "In this study, YTHDF3 proteins were mixed with HIV particles in a nucleocapsid-dependent manner, allowing the m6A reader protein to limit infection in the new target cell at the reverse transcription step, which reduced viral infectivity in the next cycle of infection." (PMID 34630412, 2021). "Next we produced single-cycle viruses in 293T-ΔYTHDF3 cells in the presence of FLAG-YTHDF3 or a control plasmid to directly determine the effects of virion incorporated YTHDF3 on the next round of infection without the interference of the endogenous YTHDF3 protein." (PMID 32053707, 2020). "Thus, our results indicate that YTHDF2, but not YTHDF1 and YTHDF3, decreases HIV-1 RNA abundance in a single round infection assay." (PMID 35101069, 2022). "Similarly, depletion of the YTHDF2, but not YTHDF1 or YTHDF3, increased the levels of HIV-1 transcripts in a single round infection assay." (PMID 35101069, 2022).
bacterial infection (1 paper, 2023). "It is believed that YTHDF1 and YTHDF3 are able to enhance the translation of target genes and facilitate inflammation by recognizing the m6A modification against bacterial infection in humans and mouse." (PMID 37298300, 2023).
metabolic disease (1 paper, 2025). A congenital disorder (due to inherited enzyme abnormality) or acquired (due to failure of a metabolically important organ) disorder resulting from an abnormal metabolic process. "Here, we unveil a previously unrecognized METTL14/METTL3/G6pc mRNA m6A/YTHDF1 and YTHDF3/G6pc biosynthesis/HGP pathway governing HGP in health and metabolic disease." (PMID 40278833, 2025).
neurological diseases (1 paper, 2023). "In frontal cortex tissues from humans with AD, the gene expression of TRMT6, TRMT61A, TRMT10C, and YTHDF3 was consistent with that observed in our verification study, indicating that mRNA m1A methylation modification also plays a key role in human neurological diseases." (PMID 37173310, 2023).
YTHDF3 also shares sentences with these, for which no sentence is quoted: atherosclerosis (4 papers); non-small cell lung carcinoma (4); Sepsis (4); cardiovascular diseases (2); diabetes (2); embryonal carcinoma (2); uterine carcinosarcoma (2); acute pancreatitis (1); acute respiratory distress syndrome (1); anaplastic thyroid carcinoma (1); aneurysm (1); autoimmune uveitis (1); Bladder Urothelial Carcinoma (1); cardiac hypertrophy (1); cervical squamous cell carcinoma (1); colitis (1); COVID-19 (1); Crohn disease (1); diffuse large B-cell lymphoma (1); digestive system neoplasm (1); endocervical adenocarcinoma (1); Enteroviral infection (1); follicular thyroid carcinoma (1); Hepatitis B (1); Hepatitis C (1); HIV-1 infection (1); Hyperglycemia (1); hypopharyngeal squamous cell carcinoma (1); inflammation (1); leukopenia (1).
A further 25 diseases each share a sentence with YTHDF3 in 1 paper.